COL1A1 (collagen type I alpha 1 chain)
Diseases named in the same sentence as COL1A1 in open-access papers (continued):
Sharing a sentence is not in itself a finding about the gene and the disease.
Ehlers-Danlos syndrome (22 papers, 2010 to 2025). The Ehlers–Danlos syndromes (EDS) are a clinically and genetically heterogeneous group of heritable connective tissue disorders (HCTDs) characterized by joint hypermobility, skin hyperextensibility, and tissue fragility. "The Col1a1Jrt/+ mouse is the first combined model of both severe-type IV OI and Ehlers Danlos Syndrome (EDS) due to a Col1a1 gene mutation leading to skipping of exon 9 and subsequent 18 amino acid deletion in the triple helical domain." (PMID 34066978, 2021). "Pathogenic variants in COL12A1, COL6A1, COL1A1, and COL5A1 have been described in individuals with different subtypes of the connective tissue disorders Ehlers-Danlos Syndrome and osteogenesis imperfecta." (PMID 33649486, 2021). "Our PPI network analysis also revealed interactions between ZNF469 and CCT candidate genes, including COL5A1, COL1A1, and other genes that regulate eyeball development, such as VSX1 (causing KC and corneal dystrophy) and CHST14 (Ehlers-Danlos Syndrome candidate gene)." (PMID 40547359, 2025). "Furthermore, the splice site mutation in the Col1a1+/Jrt mouse is positioned within the highly stable N-anchor domain (Gly1-88), in which sequence variants were reported to be associated with an OI and/or Ehlers-Danlos syndrome (EDS) outcome." (PMID 35575034, 2022). "Some other monogenetic lung disorder-related genes were enriched in specific SAE cell types, including BC (LTBP4, ELN, cutis laxa), ionoctyes (HPS5, Hermansky-Pudlak syndrome), mucin-producing cells (COL1A1, Ehlers-Danlos syndrome), and neuroendocrine cells (BMPR2, pulmonary hypertension)." (PMID 32727470, 2020). "A general connective tissue defect is seen in patients with Ehlers-Danlos syndrome (Classical EDS, which results from mutations in the COL5A1 gene), who deliver preterm due to CI or as polymorphisms in the collagen 1A1 gene (COL1A1) found in CI patients." (PMID 20673361, 2010).
Cirrhosis (21 papers, 2011 to 2026). A chronic disorder of the liver in which liver tissue becomes scarred and is partially replaced by regenerative nodules and fibrotic tissue resulting in loss of liver function. "CXCR3 knockdown suppresses TLR4/MyD88, BIRC, and COL1A1 expression, inhibits proliferation and migration, and promotes apoptosis, thereby attenuating cirrhosis-to-carcinoma transition." (PMID 41258710, 2026). "The IHC showed that the expression of COLEC10 was decreased and the expression of COL1A1 was increased in cirrhosis compared to hepatitis." (PMID 38036508, 2023). "It is compatible with our findings that COL6A1, COL6A2, and COL6A3 expressions, not COL1A1, were strongly associated with the presence of cirrhosis." (PMID 38041174, 2023). "Interestingly, MIAT expression in patients with cirrhosis was positively correlated with Col1A1 mRNA expression (r = 0.7334, p < 0.001)." (PMID 36934152, 2023). "Analyzing the cirrhosis dataset (GSE25097) revealed that the expression of SLC27A5 was negatively correlated with that of fibrosis‐related genes such as ACTA2, COL1A1, and COL3A1." (PMID 37957540, 2024). "Next, 12 cases of biopsy samples collected from patients diagnosed as hepatitis and cirrhosis were stained for COLEC10 and COL1A1." (PMID 38036508, 2023). "The mRNA expressions of alpha-1(I) collagen (Col1A1) and α-smooth muscle actin (α-SMA) were up-regulated in patients with cirrhosis." (PMID 36934152, 2023). "Elevated IGF2BP3 levels were associated with increased liver injury and fibrosis, as indicated by Col1A1 expression, suggesting that IGF2BP3 elevation may contribute to cirrhosis pathogenesis in humans." (PMID 39113232, 2024). "Taken together, it implies that PPIs among COL1A1, COL1A2, VWF and LUM may participate in the induction of cirrhosis and play roles in the progression from cirrhosis to HCC." (PMID 21526182, 2011). "CXCR4 (AUC = 0.941), COL1A2 (AUC = 0.919), CCR7 (AUC = 0.878), COL1A1 (AUC = 0.853), CXCL12 (AUC = 0.848), and CXCL8 (AUC = 0.828) had similar AUC values, demonstrating that the identified hub genes exhibited a reliable discriminatory capacity as potential biomarkers for cirrhosis." (PMID 41223189, 2025).
Hepatic steatosis (20 papers, 2018 to 2025). Steatosis is a term used to denote lipid accumulation within hepatocytes. "There was a significant increase of genes associated with hepatic steatosis (Cidea, Cidec, and Plin4) and fibrosis (Col1a1) in Adn-Lpin1–/– livers on both diets compared with their diet-matched control mice." (PMID 39405118, 2024). "In control diet fed mice, Nrf2 deficiency was nonconsequential, while Nrf1 and combined deficiency exacerbated the effect, as demonstrated by hepatic steatosis as well as significant or trending increases in hepatic triglyceride and expression of Ccl2, Ccnb1, Col1a1, Col3a1, Ihh, and Tnfrsf12a." (PMID 39125617, 2024). "Hepatic steatosis, inflammation, and fibrosis (liver lipids, galectin-3, and collagen 1a1 [Col1a1], respectively), as well as plasma alanine transaminase (ALT) and aspartate transaminase (AST) levels, were assessed." (PMID 38662778, 2024). "TNF knockout reduced the progression of hepatic steatosis and fibrosis by downregulation of MCP-1, TGF-1β, Col1a1, and TIMP-1 in transgenic mice." (PMID 31001563, 2019). "Exosomes from R patients, those exhibiting a clinical improvement of liver steatosis, were found to decrease α-SMA, COL1A1, Vimentin, and EGFR expressions by LX-2 cells (stellate cells), leading to a decrease in the extracellular matrix (ECM) protein deposition and fibrosis." (PMID 38338770, 2024). "To further determine which genes might play a significant role in the progression of fatty liver, we used real-time qPCR to detect the expression of 8 DEGs using clinical samples, including CD24, PZP, COL1A1, COL1A2, LUM, VCAN, THBS2 and EPHA3." (PMID 29769552, 2018). "However, feeding with an HFD induced more severe hepatic steatosis and fibrogenesis in Foxo1/3/4 triple knockout mice compared to wild-type mice via upregulating profibrotic genes such as C-C motif chemokine ligand 2 (CCL2), alpha-1 type I collagen (Col1A1), and TGF-β." (PMID 34359642, 2021).
osteoarthritis (20 papers, 2011 to 2025). A noninflammatory degenerative joint disease occurring chiefly in older persons, characterized by degeneration of the articular cartilage, hypertrophy of bone at the margins and changes in the synovial membrane. "For instance, Col1a1 and Col4a1 are collagen fibers that were associated with the progression of osteoarthritis." (PMID 33407721, 2021). "Notably, the ratio of COL2A1 (which encodes type II collagen) to COL1A1 expression drops dramatically as osteoarthritis progresses, indicating a shift towards a more fibroblastic phenotype in chondrocytes." (PMID 41019141, 2025). "It has been reported that the single nucleotide polymorphism (SNP) rs1800012 in COL1A1 gene might be linked to the susceptibility of musculoskeletal degenerative diseases, such as osteoarthritis (OA) and intervertebral disc degeneration (IVDD)." (PMID 29088884, 2017). "Studies have shown that the expression of COL1A1 increases significantly with higher grades of osteoarthritis severity in cartilage tissue." (PMID 41019141, 2025). "They reported a twofold increase in the mRNA ratio of Col1a1/Col1a2 in osteoarthritis bone in comparison to the control." (PMID 40647239, 2025). "Another study found a 3.4-fold increase in the mRNA expression of Col1a1 in osteoarthritis osteoblasts in comparison to normal osteoblasts." (PMID 40647239, 2025). "Another study showed that inhibiting Wnt/β-Catenin signaling through Wnt inhibitor treatment decreased COL1A1 expression in synovial fibroblasts isolated from osteoarthritis (OA) patients." (PMID 39519092, 2024). "Taken together, hyperacute serum can be a promising blood separation product in degenerative joint diseases, which enhances cell proliferation, the production of COL1A1 and osteonectin, while decreasing the level of RANKL, IL-1β, IL-6Rα, IL-12, and TNF-α." (PMID 31382623, 2019). "DOT1L inhibition enhanced the osteoarthritis-like gene expression changes, for example, augmenting loss of COL2A1 and gain of COL1A1 expression." (PMID 28627522, 2017). "In their study conducted on 64 patients (25 subjected to hip replacement surgery due to pathological fractures and 39 due to osteoarthritis), authors compared the ratios of bone OC/collagen gene expression (OC/COL1A1)." (PMID 26357654, 2015). "To address this issue, we focused our attention on the expression levels of molecules that were previously shown to be modulated during the onset of IVD degeneration or osteoarthritis (COL1A1, COL2A1, AGC1, BMP2, MMP13, MGP and P21)." (PMID 21726455, 2011). "Genes related to FAI, DDH, and osteoarthritis include COL1A1, MMP13, and IL-6." (PMID 41019141, 2025). "Genes associated with osteoarthritis, DDH, and FAI include COL1A1, MMP13, and IL-6." (PMID 41019141, 2025). "Thus, lnc-SAMD14-4 may play a key role in the pathogenesis of osteoarthritis by promoting the expression of the COL1A1 and COL1A2 genes." (PMID 31534838, 2019). "The increased expression of COL1A1, along with COL2A1, is thought to reflect the metabolic activation of chondrocytes in response to the osteoarthritis process." (PMID 41019141, 2025). "One study found increased mRNA expression in collagen type I chains, Col1a1 and Col1a2, in the hip samples of osteoarthritis patients compared to control non-osteoarthritis samples." (PMID 40647239, 2025).
osteosarcoma (20 papers, 2011 to 2025). A usually aggressive malignant bone-forming mesenchymal neoplasm, predominantly affecting adolescents and young adults. "In a second study, the same group hypothesized that variants in the estrogen receptor (ESR1), vitamin D receptor (VDR), and/or collagen 1α1 (COL1A1) gene could be osteosarcoma risk factors." (PMID 21437228, 2011). "The VDR and COL1A1 genes are required for proper bone formation and thus, if aberrations are present, could be associated with osteosarcoma." (PMID 21437228, 2011). "We further validated these candidates via the GEPIA database, narrowing down to COL1A1, PDGFRB, and SPARC as the most significantly associated with osteosarcoma progression." (PMID 41040657, 2025). "Upregulation of COL1A1 was more pronounced in chondrosarcoma and liposarcoma CSCs, and less in osteosarcoma." (PMID 41300532, 2025). "The osteosarcoma sample presented mutations involving ATRX, ERCC5, and COL1A1, while the leiomyosarcoma case showed EXT2, DNM2, and PSIP1 alterations." (PMID 36673024, 2023). "Our western blot confirmed that FN1, COL1A2, and COL1A1 were reduced expression both in osteosarcoma and Ewing's sarcoma tissues compared to normal tissues." (PMID 35578666, 2022). "Our results showed that COL1A1 was downregulated in osteosarcoma cells, which were consistent with the previous study." (PMID 35578666, 2022). "AN osteoblast-specific gain-of-function NICD1 mouse model (Col1a1 2.3kb-Cre; Rosa26NICD) developed spontaneous osteosarcoma and pulmonary metastasis." (PMID 32092942, 2020). "The gene expression for ALPL and COL1A1 was analyzed in the two osteosarcoma cell lines." (PMID 36835079, 2023). "Common key genes both in osteosarcoma and Ewing's sarcoma were identified, such as FN1, COL1A2, and COL1A1, which may act as antioncogene by enhancing cisplatin sensitivity in osteosarcoma cells and require further investigation." (PMID 35578666, 2022). "Similarly, COL1A1 also has a prognostic value in osteosarcoma patients." (PMID 32582282, 2020). "In the high TELscore group, LRP1, ITGB1, IBSP, COL1A1, and COL1A2 were the most active signaling pathways of others in osteosarcoma cells." (PMID 39980969, 2024). "According to our results, the expression of FN1, COL1A1, and COL1A2 were downregulated in osteosarcoma and Ewing's sarcoma, which often act as oncogenes, suggesting that they were more likely to play roles of antioncogene in osteosarcoma and Ewing's sarcoma." (PMID 35578666, 2022). "Our RT-qPCR results showed that FN1, COL1A2, COL1A1, and ADAMTS2 were downregulated both in osteosarcoma and Ewing's sarcoma tissues compared to normal tissues." (PMID 35578666, 2022). "Our GO enrichment analysis results showed that FN1, COL1A2, and COL1A1 were significantly enriched in the extracellular matrix, protease binding, and so on, indicating that the three genes could play a critical role in the development of osteosarcoma and Ewing's sarcoma." (PMID 35578666, 2022). "On top of that, DK1 was also capable to regulate pro-metastatic genes in both U-2 OS and MG-63 osteosarcoma cell lines; for instance, MMP3, COL1A1, and FGF expression were significantly down-regulated in U-2 OS." (PMID 34204873, 2021). "Meanwhile, some hub genes have been reported involved in the tumorigenesis and progression of osteosarcoma, such as ITGAV, POSTN, COL1A1, TGFB1, TGFB3, and ITGAV." (PMID 32582282, 2020). "It was also reported that Scx acts as a transcriptional activator for Col1a1 in tendons via binding to the E-box site CACGTG30 and Aggrecan (Acan) in osteosarcoma-derived ROS17/2.8 cells." (PMID 29453333, 2018). "Our findings suggest that COL1A1, PDGFRB, and SPARC may be involved in mtRNA-driven tumorigenesis and could serve as promising therapeutic targets for osteosarcoma." (PMID 41040657, 2025).
osteosarcoma (continued). "Our findings revealed the common oncogenic genes such as FN1, COL1A1, and COL1A2, which may act as antioncogene by enhancing cisplatin sensitivity in osteosarcoma cells, and pathways were both in osteosarcoma and Ewing's sarcoma." (PMID 35578666, 2022). "Among 12 hub genes, hub genes FN1, COL1A1, and COL1A2 may involve in the development of osteosarcoma and Ewing's sarcoma." (PMID 35578666, 2022). "The expression of early osteogenic differentiation marker genes (i.e., ALPL, RUNX-2, and COL1A1) and the ALP enzymatic activity, whose functionally mirrors the differentiation grades of osteoblastic cells, have been reported to be involved in metastasis in osteosarcoma patients." (PMID 37175397, 2023).
myopia (18 papers, 2009 to 2025). "We also investigated the molecular mechanisms underlying the attenuation of myopia development using RNA-seq and found that Col1a1 and Mmp2 expression levels were upregulated by brimonidine treatment." (PMID 34256866, 2021). "For instance, in a murine form deprivation model of myopia, disease development has been associated with changes to scleral DNA methylation at CpG sites in the collagen 1A1 (COL1A1) gene promoter and altered mRNA expression levels." (PMID 31100065, 2019). "The study found two SNPs (rs2075555 and rs2269336) were significantly associated with high myopia (p<0.05, p<0.01) and showed that COL1A1 was associated with high myopia." (PMID 22219633, 2011). "To further determine the association between COL1A1 and high myopia, we studied the association of COL1A1 with high myopia in a Han Chinese population composed of 697 subjects with high myopia and 762 matched normal controls." (PMID 22219633, 2011). "Single nucleotide polymorphisms (SNPs) in the collagen type I (COL1A1) gene have been shown to be significantly associated with high myopia in a Japanese population." (PMID 22219633, 2011). "This suggests that possible heterogeneity among different ethnicities or genetic variants in the COL1A1 gene have nothing to do with high myopia." (PMID 22219633, 2011). "In addition, the proteins encoded by Col1a1 and Mmp2 are involved in angiogenesis and the myopia pathway (among other activities) in mice and guinea pigs." (PMID 34256866, 2021). "This study, which focused specifically on the COL1A1 gene, suggested that myopia could be caused by an inhibition of scleral collagen production." (PMID 31100065, 2019). "This present study was conducted to investigate whether COL1A1 is associated with high myopia in a Han Chinese population." (PMID 22219633, 2011). "This correspondence between the declines in rs10889602 of the PDE4B gene, PDE4B knockdown, and COL1A1 protein expression levels suggest that PDE4B may be a novel high myopia susceptibility gene, which regulates myopia progression through controlling scleral collagen I expression levels." (PMID 35116054, 2021). "However, there is still some controversy regarding the association of COL1A1 and high myopia." (PMID 22219633, 2011). "In this study, it was found that both mRNA and protein expression levels of Col1A1 in the scleral tissues of guinea pigs in the myopia group were decreased, which was consistent with previous research results." (PMID 40375931, 2025). "Our results indicated a significant decrease in the expression level of COL1A1, consistent with findings observed in multiple myopia models." (PMID 38355399, 2024). "Taken together, scleral Col1a1, Col4a3, Col8a2, Col11a2, and Col15a1 expression were regulated through ER stress during the myopia progression." (PMID 36216837, 2022). "The total methylation level in the MD-T eyes was significantly greater than in the NC51 eyes, but not the MD-C eyes, because the methylation level of some CpG sites of COL1A1 in MD-C eyes also changed during myopia induction." (PMID 22690110, 2012). "In this study, we used the experimental mouse model of myopia to evaluate the methylation status of CpG sites in the promoter and exon 1 region of COL1A1 in the scleras of myopic and control eyes." (PMID 22690110, 2012). "In parallel with the development of myopia and the reduced COL1A1 mRNA, the frequency of methylation in CpG sites of the COL1A1 promoter/exon 1 increased during MD and returned to near normal during recovery." (PMID 22690110, 2012). "We also correlated the DNA methylation pattern with the expression of COL1A1 mRNA during the onset of myopia." (PMID 22690110, 2012). "A third study, which comprised 427 high myopia cases and 420 controls, analyzed eight tag SNPs, including rs2075555 and rs2269336, to tag the linkage disequilibrium blocks harboring COL1A1." (PMID 22219633, 2011).